RNU4-18P (RNA, U4 small nuclear 18, pseudogene)
Gene: Small nuclear RNA gene on chromosome 6 (131,642,818 to 131,642,966, reverse strand). Ensembl gene ENSG00000252560.
Homologues: Orthologues: chimpanzee U4 (100% identical). Paralogues in human: RNU4-74P (51% identical), RNU4-29P (50% identical), RNU4-5P (50% identical), RNU4-48P (49% identical), RNU4-39P (48% identical), RNU4-6P (48% identical), RNU4-86P (48% identical), RNU4-15P (48% identical), RNU4-9P (48% identical), RNU4-40P (47% identical), RNU4-82P (47% identical), RNU4-12P (46% identical), and 79 more.